RNF213 (ring finger protein 213)
Description:
Atypical E3 ubiquitin ligase that can catalyze ubiquitination of both proteins and lipids, and which is involved in various processes, such as lipid metabolism, angiogenesis and cell-autonomous immunity. Acts as a key immune sensor by catalyzing ubiquitination of the lipid A moiety of bacterial lipopolysaccharide (LPS) via its RZ-type zinc-finger: restricts the proliferation of cytosolic bacteria, such as Salmonella, by generating the bacterial ubiquitin coat through the ubiquitination of LPS. Also acts indirectly by mediating the recruitment of the LUBAC complex, which conjugates linear polyubiquitin chains. Ubiquitination of LPS triggers cell-autonomous immunity, such as antibacterial autophagy, leading to degradation of the microbial invader. Also functions as an intracellular sensor for ISGylated proteins: upon type I interferon stimulation, undergoes ISGylation and oligomerizes on lipid droplets to form a binding platform for ISG15-modified substrate proteins, thereby acting as a broad-spectrum antimicrobial effector. Restricts intracellular bacterial pathogens, such as Listeria monocytogenes, in an ISG15-dependent manner by decorating the bacterial surface with ubiquitin to promote autophagic clearance. Involved in lipid metabolism by regulating fat storage and lipid droplet formation; act by inhibiting the lipolytic process. Also regulates lipotoxicity by inhibiting desaturation of fatty acids. Also acts as an E3 ubiquitin-protein ligase via its RING-type zinc finger: mediates 'Lys-63'-linked ubiquitination of target proteins. Involved in the non-canonical Wnt signaling pathway in vascular development: acts by mediating ubiquitination and degradation of FLNA and NFATC2 downstream of RSPO3, leading to inhibit the non-canonical Wnt signaling pathway and promoting vessel regression. Also has ATPase activity; ATPase activity is required for ubiquitination of LPS.
Synonyms: ALO17; C17orf27; KIAA1554; KIAA1618; MYSTR; NET57; MYMY2
Tractability: Small molecule: a structure with a bound ligand is known. PROTAC: UniProt records ubiquitination sites on it; ubiquitination databases record sites on it; its protein half-life has been measured.
Target class: Enzyme; Transferase
Gene: Protein-coding gene on chromosome 17 (80,260,852 to 80,398,794, forward strand). Ensembl gene ENSG00000173821.
Subcellular location: Cytoplasm, cytosol; Lipid droplet
Subcellular location (Human Protein Atlas): Cytosol
Pathways (Reactome):
Disease: Signaling by ALK fusions and activated point mutants; Suppression of apoptosis
Immune System: Antigen processing: Ubiquitination & Proteasome degradation
Gene Ontology:
Molecular function: ATP hydrolysis activity; ubiquitin protein ligase activity; ubiquitin-protein transferase activity; metal ion binding
Biological process: angiogenesis; defense response to bacterium; lipid droplet formation; lipid ubiquitination; negative regulation of non-canonical Wnt signaling pathway; protein autoubiquitination; protein K63-linked ubiquitination; protein ubiquitination; regulation of lipid metabolic process; sprouting angiogenesis; ubiquitin-dependent protein catabolic process; xenophagy
Cellular component: cytoplasm; cytosol; lipid droplet; membrane
Genetic constraint (gnomAD): Loss-of-function variants: 323 observed, 511.71 expected, observed/expected ratio (o/e) 0.63, 90% interval 0.57 to 0.69. The upper end of that interval is the gene's LOEUF score, 0.69, which puts it in group 2 of 6, group 1 being the genes least tolerant of losing a copy. Missense variants: 5,662 observed, 6,779.2 expected, observed/expected ratio (o/e) 0.84, 90% interval 0.82 to 0.85. Synonymous variants: 2,613 observed, 2,732.6 expected, observed/expected ratio (o/e) 0.96, 90% interval 0.93 to 0.99.
Cancer hallmarks: angiogenesis (promotes)
Homologues: Orthologues: chimpanzee RNF213 (98% identical), macaque RNF213 (89% identical), dog RNF213 (67% identical), mouse Rnf213 (67% identical), rat Rnf213 (66% identical), zebrafish rnf213a (45% identical).
Diseases named in the same sentence as RNF213 in open-access papers:
RNF213 is named in the same sentence as 146 diseases in open-access papers, as found by Europe PMC text mining. Sharing a sentence is not in itself a finding about the gene and the disease. The quoted sentences say what the papers report.
Moyamoya disease (109 papers, 2011 to 2026). Moyamoya disease (MMD) is a rare intracranial arteriopathy involving progressive stenosis of the cerebral vasculature located at the base of the brain causing transient ischemic attacks or strokes. "For example, users can query and browse for m6A coordinates and abundances located at gene RNF213, which is widely recognized as the major genetic susceptibility factor for Moyamoya disease (MMD), using the gene symbol name in the search box." (PMID 41330425, 2026). "In larger cohorts, the RNF213 (c.14576G > A) mutation was reported in 69.9% to 85.4% of moyamoya disease cases." (PMID 40869930, 2025). "Distinct RNF213 variants, such as p.Asn4013Asp and p.Arg4062Glu, have been documented in White patients with moyamoya disease." (PMID 40869930, 2025). "The RNF213 gene, located on chromosome 17q25.4, is a key susceptibility gene for moyamoya disease, with multiple single nucleotide polymorphisms (SNPs) identified." (PMID 40682695, 2025). "The identification and reporting of novel RNF213 variants in adults with adult-onset moyamoya disease are critical to advancing our understanding of the disease’s heterogeneous manifestations." (PMID 40682695, 2025). "Following Bonferroni correction for multiple comparisons, targeted analyses of RNF213 and 36 moyamoya angiopathy-related genes showed a significant association of only RNF213 p.Arg4810Lys with favorable DTA development (P = 0.001)." (PMID 38592555, 2025). "The ring finger protein 213 (RNF213) Arg4810Lys variant has been previously identified as a significant risk factor for Moyamoya disease (MMD), particularly in East Asian populations." (PMID 40869185, 2025). "Further research is warranted to clarify the role of RNF213 polymorphisms in disease progression and their impact on adult-onset moyamoya disease phenotypes." (PMID 40682695, 2025). "RNF213 is the first identified susceptibility gene for moyamoya disease, and the encoded protein was recently recognized as a key antimicrobial protein." (PMID 40623121, 2025). "Mutations in RNF213 cause Moyamoya disease, a rare cerebrovascular disorder caused by intimal thickening and occlusion of the terminal portion of the internal carotid artery." (PMID 40205224, 2025). "One area of particular interest is the emerging field of RNF213-related vasculopathy, which has been implicated in various cerebrovascular disorders, including the moyamoya disease (MMD) and intracranial arterial stenosis." (PMID 39858606, 2025). "These conditions can sometimes co-occur with moyamoya disease, particularly in the carriers of the homozygous RNF213 p.Arg4810Lys mutation." (PMID 40869930, 2025). "One of these is the gene RNF213, which encodes the ring finger protein 213, and variants in this gene have been linked to Moyamoya disease, arterial stenosis/occlusion, atherosclerosis, ischemic stroke and intracranial aneurysms." (PMID 39982482, 2025). "The RNF213 p.R4810K heterozygous variant has been reported not only in patients with moyamoya disease, but also in approximately 8% of patients diagnosed with idiopathic pulmonary arterial hypertension." (PMID 39803001, 2024). "The RNF213 gene, especially the R4810K (p.R4757K) variant, is a key genetic factor associated with moyamoya disease (MMD)." (PMID 39195567, 2024). "Although positive selection has acted mainly on the N-terminus of RNF213, mutations in patients with Moyamoya disease cluster towards the C-terminus and are primarily found in the E3 module." (PMID 39375464, 2024). "Advances in stroke genetics have highlighted the critical role of rare genetic variants in cerebrovascular diseases, with RNF213 emerging as a key player in ischemic stroke and Moyamoya disease (MMD)." (PMID 39857601, 2024). "Mutations in the RNF213 gene have been identified in relation to an increased risk of Moyamoya disease and aneurysm development." (PMID 39125654, 2024).
Moyamoya disease (continued). "At present, it is clear that the mutant of RNF213 is a susceptibility gene for Moyamoya disease, and RNF213 also plays a dangerous role in other cerebrovascular diseases such as intracranial aortic stenosis/occlusion and intracranial aneurysms." (PMID 39125654, 2024). "RNF213 is an established susceptibility gene associated with moyamoya disease, and its important role in tumor suppression via modulation of the MAPK/JNK signaling pathway has been reported in glioblastoma." (PMID 39338204, 2024). "The ring finger protein 213 (RNF213) p.R4810K variant has been identified as being associated with Moyamoya disease (MMD), a condition that is more prevalent in East Asians." (PMID 38115307, 2023). "Ring finger protein 213 (RNF213) is a large E3 ubiquitin ligase with a molecular weight of 591 kDa that is associated with moyamoya disease, a rare cerebrovascular disease." (PMID 37655297, 2023). "Lastly, in one patient, a heterozygous variant (p.Arg4019Cys) in RNF213, a susceptibility gene in Moyamoya disease, was present." (PMID 36411388, 2023). "Although RNF213 has been widely studied as a cause of moyamoya disease (MMD), it also plays important roles in other cellular processes and has been implicated in the immune response to pathogenic infections." (PMID 37655297, 2023). "In 2016, our group identified 2 patients with a homozygous mutation of RNF213, p.Arg4810Lys, who developed moyamoya disease and severe pulmonary hypertension caused by peripheral pulmonary artery stenosis." (PMID 35455046, 2022). "Familial patients with moyamoya disease showed a strong association with the RNF213 pathogenetic variants (odds ratio, 4.54), consistent with the case of the Asian population." (PMID 35455046, 2022). "These cases all point to the RNF213 gene, so it is possible that patients with moyamoya disease associated with variants of the RNF213 gene have unique liver and kidney phenotypes." (PMID 36090342, 2022). "The variants of RNF213, especially the p.Arg4810Lys variant, have been identified as a key moderator of development in moyamoya disease." (PMID 35455046, 2022). "Although the RNF213 p.Arg4810Lys variant was hardly detected, several pathogenetic variants of RNF213 have been identified in Caucasian patients with moyamoya disease." (PMID 35455046, 2022). "We investigated the impact of the p.R4810K variant of RNF213 (ring finger protein 213) gene, a susceptibility gene of moyamoya disease in East Asia, on the outer diameter of cervical parts of carotid and vertebral arteries (VAs)." (PMID 41582976, 2022). "The association of RNF213 p.Arg4810Lys as a susceptibility variant of moyamoya disease was reproduced in Korean and Chinese individuals and, later, in Caucasians." (PMID 35455046, 2022). "The association of RNF213 p.Arg4810Lys as a susceptibility variant of moyamoya disease was reproduced in Korean and Chinese individuals." (PMID 35455046, 2022). "A mutation in RNF213 (c.14576G>A), a gene associated with moyamoya disease (>80%), plays a role in terminal internal carotid artery (ICA) stenosis (>15%) (ICS)." (PMID 34680863, 2021). "The cases also suggest a new, multi‐organ RNF213‐spectrum disease characterized by liver, skin, and kidney pathology in addition to severe moyamoya disease caused by heterozygous, de novo C‐terminal RNF213 missense variants." (PMID 33960657, 2021). "What’s more, moyamoya diseases, which used to be considered as a rare polygenic cerebrovascular disease, is also known to be associated with some susceptibility genes especially RNF213 p.R4810K and human leukocyte antigen (HLA)." (PMID 34736485, 2021). "Moyamoya disease, for which RNF213 was discovered in 2011 to be a disease susceptibility gene, is an occlusive disease of the bilateral ICA terminations occurring from childhood." (PMID 34680863, 2021). "RNF213 is a poorly characterized, interferon-induced megaprotein that is frequently mutated in Moyamoya disease, a rare cerebrovascular disorder." (PMID 34599178, 2021).
Moyamoya disease (continued). "The East Asian-specific p.R4810K variant of RNF213, a susceptibility gene for moyamoya disease (MMD), accounts for up to 25% of sporadic ischemic stroke with ICA stenosis cases in East Asia." (PMID 33482763, 2021). "Pathogenic variants in the RNF213 gene are linked to Moyamoya disease, which is probably multifactorial and polygenic disease with various clinical presentations and inheritance type." (PMID 34573383, 2021). "These cases highlight the ability of RNF213 to cause Mendelian moyamoya disease in addition to acting as a genetic susceptibility locus." (PMID 33960657, 2021). "RNF213 has been identified as a susceptibility gene of Moyamoya disease, intracranial arterial stenoses, and systemic vasculopathy among East Asian populations and CAD in the Japanese population." (PMID 33632238, 2021). "Mutations in RNF213 are associated with predisposition for Moyamoya disease (MMD), a rare cerebrovascular disorder." (PMID 34804992, 2021). "Ring finger protein 213 (RNF213) is a susceptibility gene of moyamoya disease and plays an important role in vascular development." (PMID 34753383, 2021). "RNF213 was originally demonstrated as a susceptibility gene for moyamoya disease (MMD), which is characterized by progressive arterial stenosis and occlusion around the circle of Willis26." (PMID 32686731, 2020). "Human RNF213, which encodes the protein mysterin, is a known susceptibility gene for moyamoya disease (MMD), a cerebrovascular condition with occlusive lesions and compensatory angiogenesis." (PMID 32342250, 2020). "Variants in RNF213 predispose to Moyamoya disease in diverse ethnicities, and rare variants have been recently identified in 25 from 249 patients with IA/SAH in a French Canadian population." (PMID 32367296, 2020). "RNF213 is the major susceptibility factor for Moyamoya disease, a progressive cerebrovascular disorder that often leads to brain stroke in adults and children." (PMID 32573437, 2020). "hiPSC-ECs were also used in the investigation of Moyamoya disease and the RNF213 R4810K polymorphism, which makes the carriers more susceptible to this cerebrovascular pathology." (PMID 32887493, 2020). "A previous study showed a strong association between the p.R4810K mutation in RNF213, which has a relatively high prevalence among East Asians and is a risk factor for the development of Moyamoya disease." (PMID 30777110, 2019). "Rnf213 encodes a type Zn-finger protein involved in mediating protein-protein interactions and has been reported as a susceptibility gene for Moyamoya disease, a vascular disorder of intracranial arteries." (PMID 31620112, 2019). "Ring finger protein 213 (RNF213) was originally identified as a susceptibility gene for moyamoya disease (MMD)." (PMID 31815282, 2019). "On the other hand, RNF213 (mysterin) is a large (591 kD) ATPase/E3 ligase, which is mostly known as being a susceptibility gene for moyamoya disease (cerebrovascular disease)." (PMID 30979826, 2019). "Very recently, and for the first time, the FREX consortium reported rare variants in the C-terminal region of RNF213 associated with moyamoya angiopathy in patients of European ancestry." (PMID 30001348, 2018). "RNF213 (Ring Finger Protein 213)/mysterin is recognised as a major susceptibility gene for moyamoya disease (MMD), which is a progressive steno-occlusive disease of the cerebral arteries." (PMID 29483617, 2018). "Very recently, rare missense variants in the C-terminal region of RNF213 were associated with moyamoya angiopathy in patients of European ancestry." (PMID 30001348, 2018). "In recent years, the ring finger protein 213 gene (RNF213) has gradually attracted attention, mainly because it has been found that RNF213 c.14429 G>A is associated with moyamoya disease (MMD) in East Asian populations." (PMID 30671466, 2018). "We applied the BDC approach for the 214 kb autosomal region, ring finger protein 213, which is the susceptibility gene of moyamoya disease (MMD)." (PMID 30001370, 2018).